INS (insulin)
Diseases named in the same sentence as INS in open-access papers (continued):
Sharing a sentence is not in itself a finding about the gene and the disease.
type 1 diabetes (continued). "This is especially true in type 1 diabetes, as baseline insulin values must be met to prevent diabetic ketoacidosis." (PMID 26078998, 2015). "In type 1 diabetes, the hepatic tissue cannot synthesize glycogen due to defective glucose mobilization as a result of the decreased insulin secretion." (PMID 25793188, 2015). "As insulin-producing cells, the dysfunction of pancreatic β-cells is considered as a major factor contributing to the development of both type 1 diabetes (T1D) and type 2 diabetes (T2D)." (PMID 26335571, 2015). "The aim of this study was to compare the pharmacokinetics of two different concentrations of insulin aspart (B28Asp human insulin) in children aged 3–6 years with type 1 diabetes." (PMID 25537835, 2015). "In contrast, when people with type 1 diabetes consume protein, there is an increase in postprandial BGLs and insulin requirements." (PMID 26202844, 2015). "Type I diabetes is an immunologically-mediated devastation of insulin producing cells (IPCs) in the pancreatic islet." (PMID 26199902, 2015). "In patients with type 1 diabetes who undergo basal-bolus insulin therapy with multiple daily injections, basal insulin is largely responsible for the stability of blood glucose levels in the fasting state." (PMID 26044206, 2015). "Type I diabetes (T1D), mediated by autoreactive T cell destruction of insulin-producing islet beta cells, has been treated with bone marrow-derived hematopoietic stem cell (BM-HSC) transplantation." (PMID 26020954, 2015). "Several combination therapies can reverse type 1 diabetes in NOD mice, indicating the possible recovery of endogenous insulin production in this type 1 diabetes model." (PMID 25338552, 2015). "The mean value of tmax in the present study (60.4 min) is comparable with that reported in older children and adults with type 1 diabetes following insulin bolus injection (49 min) or during closed-loop insulin delivery (66 min and 51 min, respectively)." (PMID 25537835, 2015). "Type 1 diabetes is the result of a selective autoimmune destruction of insulin-producing beta-cells, characterized by islet inflammation (insulitis), which leads to chronic hyperglycemia." (PMID 26339637, 2015). "Type III diabetes differs from type I diabetes as the damage of pancreatic islets is not limited to insulin secreting beta cells but is more diffused as it also affects glucagon and pancreatic polypeptide secreting alpha and PP cells." (PMID 25892991, 2015). "Type 1 diabetes (T1D) is an autoimmune disease that permanently destroys the insulin-producing cells in the pancreatic islets as a consequence of T-lymphocyte mediated autoimmunity." (PMID 25604067, 2015). "Hypoglycemia is a common and serious problem among patients with type 1 diabetes receiving treatment with insulin." (PMID 25761767, 2015). "Before the availability of insulin, Type 1 diabetes was highly fatal in the first years following diagnosis, as illustrated by the experience of the Joslin Clinic." (PMID 26259708, 2015). "In the treatment of this patient with type 1 diabetes and adult-type cyclic vomiting syndrome, continuous subcutaneous insulin infusion therapy and comprehensive psychotherapy were effective." (PMID 26401489, 2015). "Type 1 diabetes (T1D) is an autoimmune disease that is characterized by the specific destruction of insulin‐producing pancreatic β cells." (PMID 26734463, 2015). "For example, a child with known type I diabetes was admitted as result of severe hypoglycemia following insulin injection." (PMID 26173560, 2015). "The identification of type 1 diabetes in diabetic subjects receiving insulin therapy is sometimes difficult." (PMID 25621692, 2015). "Today, type 1 diabetes mellitus (T1DM) is considered an autoimmune disease with a T-cell mediated destruction of the insulin producing beta cells in the pancreas." (PMID 26181330, 2015).
type 1 diabetes (continued). "Currently, treatments for women with type 1 diabetes who are seeking pregnancy include dietary modifications and insulin treatment to help stabilize the blood sugar." (PMID 26002932, 2015). "Taken together, our findings show the disruption of the body temperature daily rhythm, a new consequence of insulin-dependent diabetes, as well as the beneficial effect of the complementary action of melatonin and insulin restoring the normal rhythmicity." (PMID 25960780, 2015). "This article will therefore review the evidence regarding the glycaemic impact of fat and protein and discuss the clinical implications and mealtime insulin dosing strategies in the management of type 1 diabetes." (PMID 26202844, 2015). "Herein, we present two patients with type 1 diabetes treated with CSII in whom peak action of breakfast insulin boluses is too delayed to achieve adequate postprandial glucose control but causes late episodes of hypoglycemia." (PMID 25614824, 2015). "Little information exists on the trajectory and determinants of adiponectin, a possible insulin sensitizer and marker for inflammation and endothelial function, across the duration of type 1 diabetes." (PMID 25950008, 2015). "In type I diabetes, the primary reduction of insulin levels due to the autoimmune mediated damage of islet cells results in a decreased trophic action on the exocrine cells." (PMID 25892991, 2015). "On the one hand, insulin secretion is known to be affected by immunoreactivity to insulin in type 1 diabetes (T1D) in humans." (PMID 25743104, 2015). "Our study confirms that in this population LADA subjects are clinically different from type 2 and type 1 diabetes and suggests that the clinical phenotype can depend on different patterns of antibody positivity influencing the time to insulin requirement." (PMID 26252955, 2015). "We found that professional CGM is useful for the identification of type 1 diabetes among diabetic subjects receiving insulin therapy." (PMID 25621692, 2015). "Our data demonstrated that the use of data derived from professional CGM provided a predictive advantage for type 1 diabetes among diabetic patients with advanced insulin therapies." (PMID 25621692, 2015). "Newly diagnosed diabetics accounted for 15 (25%) of the cases; the remainder were known cases of type 1 diabetes on insulin treatment." (PMID 26870116, 2015). "The objective of this field study was to evaluate the feasibility and acceptability of decision coaching guided by the OFDG with children and parents considering insulin delivery options for type 1 diabetes management." (PMID 25889602, 2015). "Type 1 diabetes (T1D) is an autoimmune disease in which the immune system is activated against the insulin producing β-cells present in the pancreatic islets." (PMID 26347378, 2015). "By the end of the activity, students were asked to illustrate insulin signaling in a healthy individual compared to an individual with type I diabetes." (PMID 25856580, 2015). "The damage of insulin-producing beta cells that occur in type 1 diabetes decreases insulin availability, leading to hyperglycemic state." (PMID 26783951, 2015). "Type 1 diabetes is a well-known prototypic tissue specific autoimmune disease that results from auto-reactive lymphocyte destruction of the pancreatic islet insulin-producing β-cells." (PMID 25714914, 2015). "Historically these are likely to be patients with type 1 diabetes, for whom insulin therapy is a mainstay." (PMID 25943590, 2015). "Currently, patients with type 1 diabetes are treated with either multiple daily injections (MDI) or continuous subcutaneous insulin infusion (CSII) delivering via an insulin pump." (PMID 26550021, 2015). "The present study investigated the efficacy and safety of switching from twice-daily basal insulin injections to once-daily insulin degludec injection in Japanese patients with type 1 diabetes." (PMID 26435713, 2015).
type 1 diabetes (continued). "Approximately 10% of diabetic patients have type 1 diabetes (usually starting in childhood or younger age), and these patients have an absolute requirement for insulin therapy requiring daily dosage of insulin." (PMID 25866760, 2015). "Type 1 diabetes is caused by autoimmune destruction of β- cells, therefore, treatment of type 1 diabetes depends on exogenous insulin." (PMID 26131436, 2015). "In this paper, we propose a decision support tool for setting basal insulin therapy at the onset of type 1 diabetes." (PMID 25888901, 2015). "Type 1 diabetes is a T cell mediated autoimmune disease characterised by exogenous insulin dependency resulting from the destruction of the insulin-producing beta cells." (PMID 25652388, 2015). "In conclusion, glycemic control under once-daily insulin degludec injection was almost comparable to that under twice-daily basal insulin injections in Japanese type 1 diabetes patients." (PMID 26435713, 2015). "Restoration of endogenous insulin production by islet transplantation is considered a curative option for patients with type 1 diabetes." (PMID 26080071, 2015). "We compared the SD and CV of FPG levels in individuals with type 1 diabetes treated with basal-bolus insulin therapy using either IDeg or IGlar." (PMID 26044206, 2015). "People with type 1 diabetes must inject themselves with insulin and follow a careful diet and exercise." (PMID 26330860, 2015). "Type 1 diabetes is an autoimmune disorder in which auto-reactive T-cells selectively destroy the pancreatic islet insulin-producing beta cells." (PMID 26378585, 2015). "A few studies from Japan have already investigated the outcome of switching from once-daily or twice-daily basal insulin to once-daily insulin degludec in patients with type 1 diabetes." (PMID 26435713, 2015). "Type 1 diabetes is a common disease in which insulin-producing pancreatic β cells are impaired by immune-mediated mechanisms." (PMID 26002932, 2015). "A decision about type 1 diabetes insulin delivery was selected because it is a common decision that has implications for both the child and parents given the benefits, risks and inconveniences of different insulin delivery options." (PMID 25889602, 2015). "In Brazil, only a few states provide insulin analogues for patients with type 1 diabetes under multiple and varying criteria." (PMID 25964802, 2015). "Insulin analogues and the assumption they would better mimic the pharmacokinetic profile of endogenous insulin secretion emerged as a magic bullet in the treatment of patients with type 1 diabetes." (PMID 25964802, 2015). "Type 1 diabetes (T1D) results from autoimmune destruction of β cells, the insulin-producing cells in the pancreatic islets of Langerhans." (PMID 26690959, 2015). "Type 1 diabetes results from the autoimmune destruction of insulin-secreting pancreatic beta cells by T cells." (PMID 25652388, 2015). "Further study is needed to strengthen our evidence obtained from this study with combined therapy applying both exercise and insulin injection in type 1 diabetic animal model." (PMID 25964060, 2015). "This field study showed that decision coaching with the OFDG was acceptable to parents and children considering insulin options for type 1 diabetes management and was feasible to measure." (PMID 25889602, 2015). "Currently, the only therapy for type 1 diabetes is administration of insulin and/or analogues (which differ from human insulin by one or two amino acids)." (PMID 25866533, 2015). "As STZ is a model of type 1 diabetes, our findings imply that insulin action in skeletal muscle couples directly to mitochondrial energetics and substrate selection." (PMID 26197936, 2015). "Type 1 diabetes is a T cell-mediated autoimmune disease in which the insulin-producing pancreatic beta cells are selectively destroyed; this disease is most often diagnosed in children and young adults." (PMID 26113264, 2015).
type 1 diabetes (continued). "Around the same time, there was evidence to suggest that high-fat and high-protein meals influence exogenous insulin requirements in type 1 diabetes, however these were largely overlooked in the enthusiasm for carbohydrate counting (." (PMID 26202844, 2015). "In type-1 diabetes, the insulin-producing β-cells are destroyed and patients require lifelong treatment with exogenous insulin." (PMID 25145789, 2014). "Using recommended values for fasting and post-glucagon stimulated C- peptide levels in type 1 diabetes, 10 (21%) of the subjects studied were classified as insulin-dependent while the remaining 36 (78%) were classified as insulin-treated." (PMID 25945127, 2014). "Insulin detemir and insulin glargine each had perceived advantages in the treatment of children with type 1 diabetes." (PMID 24653838, 2014). "This likely reflects the persisting absolute requirement for insulin therapy in patients with type 1 diabetes, as a result of immunological β-cell destruction and absolute insulin deficiency." (PMID 24668543, 2014). "Type 1 diabetes is a chronic disease that results from autoimmune destruction of insulin-producing beta cells of the pancreas." (PMID 24637957, 2014). "The plasma C-peptide has proved to be extremely valuable in the study of the natural history of type 1 diabetes to monitor insulin secretion in patients with insulin antibodies and as an adjunct in the investigation of patients with hypoglycemic disorders." (PMID 25309773, 2014). "Type 1 (also known as insulin-dependent diabetes or juvenile diabetes) results from an autoimmune attack destroying the insulin producing beta cells of the pancreas." (PMID 26852676, 2014). "Plasma levels of IAPP and insulin deviate in a subpopulation of young with newly-diagnosed type 1 diabetes." (PMID 24671002, 2014). "Patients with type 1 diabetes (T1DM) require treatment with multiple subcutaneous insulin injections daily." (PMID 24739875, 2014). "Serum level of GPI-PLD was increased in human and rodent type 1 diabetes, but it was reduced by treatment with insulin." (PMID 24971987, 2014). "In patients suffering from type 1 diabetes, high-fat meals containing identical carbohydrate and protein contents required a larger dose of insulin than low-fat meals." (PMID 25222490, 2014). "Type-1 diabetes is an autoimmune disease in which the body's own immune cells attack islet β cells, the cells in the pancreas that produce and release the hormone insulin." (PMID 25549298, 2014). "In fact, although cytoprotective properties on renal tissue derived from the amelioration of insulin cannot be excluded, the results obtained in type 1 diabetes models suggest extra-pancreatic (renoprotective) effects of GLP-1/GLP-1R." (PMID 24817793, 2014). "Given the limited studies in this increasingly obese population, we investigated the short-term effects of GB on weight, HbA1c, and insulin requirements in obese subjects with type 1 diabetes." (PMID 24668543, 2014). "Children and adolescents with type-1 diabetes mellitus often have serious difficulties with adjustment of the insulin dose." (PMID 25563223, 2014). "In conclusion, we demonstrate that GB decreases BMI, HbA1c, and insulin requirements in severely obese women with type 1 diabetes." (PMID 24668543, 2014). "Another study examined the AUC of insulin concentration in children and adolescents with type 1 diabetes." (PMID 24653838, 2014). "Our results provide an opportunity to use non-genetic means to compensate lessefficient splicing and lower INS expression from haplotypespredisposing to type 1 diabetes." (PMID 24944197, 2014). "Of 1,423 patients with at least 2 insulin prescriptions and/or hospital admissions because of type 1 diabetes, 1,107 incident insulin users met the inclusion criteria." (PMID 24498320, 2014).
type 1 diabetes (continued). "Another practical disadvantage of transplantation is that 2 × 106 of β-cells per kg of patient body weight are necessary to achieve good metabolic control by production of insulin in type I diabetes." (PMID 25526563, 2014). "The DCCT demonstrated that the maintenance of glycemia close to normal levels during intensive insulin therapy reduces the incidence and seriousness of chronic complications in type 1 diabetes." (PMID 24790575, 2014). "A first study reported decreased insulin requirements in new-onset type 1 diabetics by addition of sitagliptin to exogenous insulin therapy (NCT01235819)." (PMID 25268801, 2014). "Severe hypoglycemia is a major complication of insulin treatment in patients with type 1 diabetes, limiting full realization of glycemic control." (PMID 25289645, 2014). "Type 1 diabetes (T1D) is an autoimmune disease characterized by destruction of the insulin-producing β-cells in the pancreatic islets." (PMID 24465825, 2014). "Kurtoglu and colleagues examined children with type 1 diabetes who switched from insulin NPH or glargine to detemir and found improved HbA1c along with fewer hypoglycemic events." (PMID 24653838, 2014). "Similar observations of preserved insulin production with high-dose anti-CD3 were seen in the Autoimmunity-Blocking Antibody for Tolerance in Recently Diagnosed Type 1 Diabetes (AbATE) study." (PMID 25185797, 2014). "Type 1 diabetes is an insulin-dependent, autoimmune disorder characterized by the destruction of insulin-producing β-cells." (PMID 24297321, 2014). "Currently, patients with type-1 diabetes must rely on regular injections of insulin to prevent their blood sugar level from rising too high (a condition called hyperglycaemia)." (PMID 25549298, 2014). "The proof of concept that empagliflozin is effective in lowering glucose and sparing insulin has been recently demonstrated in a preclinical model of STZ-induced type 1 diabetes but also in human studies." (PMID 25402275, 2014). "Islets encapsulated in immunoprotective microcapsules are being proposed as an alternative for insulin therapy for treatment of type 1 diabetes." (PMID 25147785, 2014). "Type 1 diabetes results from the selective and progressive destruction of insulin-producing cells by autoreactive CD8+ T cells and a variable number of bystander CD8+ T cells." (PMID 25073445, 2014). "Patients with type 1 diabetes (n = 153) using continuous subcutaneous insulin infusion (CSII) were randomized to a 12 month sensor-On/Off or sensor-Off/On sequence (6 months each treatment), with a 4-month washout between periods." (PMID 25037251, 2014). "In the case of type 1 diabetes (T1D), metabolic impairment is the result of autoimmune destruction of insulin-producing pancreatic β-cells." (PMID 25071830, 2014). "The present study was therefore designed to evaluate a standardized composition, UP780, an aloe chromone formulated with an aloe polysaccharide, improves insulin sensitivity in alloxan induced insulin dependent diabetic mice." (PMID 24891878, 2014). "Type 1 diabetes is a juvenile onset form of diabetes resulting from autoimmune destruction of insulin-producing β cells in the pancreatic islets of Langerhans." (PMID 24877157, 2014). "Type 1 diabetes (T1D) is an autoimmune disorder whereby autoreactive T cells destroy insulin-producing cells in pancreatic islets." (PMID 25215657, 2014). "In conclusion, we were able to detect enduring low-level insulin production in the majority of patients with type 1 diabetes, even in those with very long disease duration." (PMID 24121625, 2014). "Regular body exercise related effects on the decrease of insulin resistance and non-insulin dependent diabetes have been emphasized in several studies." (PMID 25560330, 2014). "It was a landmark discovery in the medical science when insulin was purified from bovine and porcine pancreas and was utilized as a life-saving injection for patients with type I diabetes mellitus (T1DM) in 1922." (PMID 25126554, 2014).